RBM25 (RNA binding motif protein 25)
Description:
RNA-binding protein that acts as a regulator of alternative pre-mRNA splicing. Involved in apoptotic cell death through the regulation of the apoptotic factor BCL2L1 isoform expression. Modulates the ratio of proapoptotic BCL2L1 isoform S to antiapoptotic BCL2L1 isoform L mRNA expression. When overexpressed, stimulates proapoptotic BCL2L1 isoform S 5'-splice site (5'-ss) selection, whereas its depletion caused the accumulation of antiapoptotic BCL2L1 isoform L. Promotes BCL2L1 isoform S 5'-ss usage through the 5'-CGGGCA-3' RNA sequence. Its association with LUC7L3 promotes U1 snRNP binding to a weak 5' ss in a 5'-CGGGCA-3'-dependent manner. Binds to the exonic splicing enhancer 5'-CGGGCA-3' RNA sequence located within exon 2 of the BCL2L1 pre-mRNA. Also involved in the generation of an abnormal and truncated splice form of SCN5A in heart failure.
Synonyms: RED120; RNPC7; S164; fSAP94; NET52; Snu71
Tractability: PROTAC: UniProt records ubiquitination sites on it; ubiquitination databases record sites on it; its protein half-life has been measured.
Gene: Protein-coding gene on chromosome 14 (73,058,532 to 73,123,899, forward strand). Ensembl gene ENSG00000119707.
Subcellular location: Nucleus speckle; Cytoplasm
Subcellular location (Human Protein Atlas): Nuclear speckles
Pathways (Reactome):
Metabolism of RNA: mRNA Polyadenylation; mRNA Splicing - Major Pathway
Gene Ontology:
Molecular function: mRNA binding; protein binding; RNA binding; nucleic acid binding
Biological process: regulation of alternative mRNA splicing, via spliceosome; regulation of apoptotic process
Cellular component: nuclear speck; nucleoplasm; cytoplasm
Genetic constraint (gnomAD): Loss-of-function variants: 13 observed, 104.64 expected, observed/expected ratio (o/e) 0.12, 90% interval 0.08 to 0.2. The upper end of that interval is the gene's LOEUF score, 0.2, which puts it in group 1 of 6, group 1 being the genes least tolerant of losing a copy. Missense variants: 577 observed, 1,002.7 expected, observed/expected ratio (o/e) 0.58, 90% interval 0.54 to 0.62. Synonymous variants: 366 observed, 317.81 expected, observed/expected ratio (o/e) 1.15, 90% interval 1.06 to 1.26.
Homologues: Orthologues: chimpanzee RBM25 (100% identical), dog RBM25 (99% identical), macaque RBM25 (99% identical), guinea pig RBM25 (99% identical), pig RBM25 (99% identical), rabbit RBM25 (99% identical), mouse Rbm25 (99% identical), rat Rbm25 (99% identical), rat Rbm25l1 (93% identical), tropical clawed frog rbm25 (85% identical), zebrafish rbm25b (74% identical), Drosophila melanogaster CG4119 (39% identical), and 1 more.
Diseases named in the same sentence as RBM25 in open-access papers:
RBM25 is named in the same sentence as 25 diseases in open-access papers, as found by Europe PMC text mining. Sharing a sentence is not in itself a finding about the gene and the disease. The quoted sentences say what the papers report.
acute myeloid leukemia (5 papers, 2019 to 2022). Acute myeloid leukemia (AML) is a group of neoplasms arising from precursor cells committed to the myeloid cell-line differentiation. "Splicing regulator RBM25 was identified as a tumor suppressor in acute myeloid leukemia, and the low level of RBM25 was associated with high MYC activity and poor prognosis of patients." (PMID 34386035, 2021). "In acute myeloid leukemia, RBM25 controls the splicing of key genes." (PMID 33830865, 2021). "As a splicing factor, RBM25 contributes to regulating MYC activity in acute myeloid leukemia." (PMID 34650978, 2021). "RBM25, TARDBP, and CELF1 were found to be correlated with many CASEs, among which RBM25 was thought to inhibit the progression of acute myelogenous leukemia by affecting MYC activity." (PMID 35126520, 2022). "While RBM25 has not been previously reported to be involved in HCC, it has been proven to be important in the occurrence and development of acute myeloid leukemia, prostate cancer, and colorectal cancer." (PMID 33830865, 2021).
heart failure (5 papers, 2019 to 2025). Inability of the heart to pump blood at an adequate rate to meet tissue metabolic requirements. "RBM25 is a poorly characterized RNA binding protein that has previously been implicated in specific splicing events in human heart failure and as a crucial factor for plant growth and abiotic stresses in Arabidopsis37–39." (PMID 30635567, 2019). "Hypoxia and angiotensin II signals activate splicing factors like RNA-binding motif protein 25 (RBM25) and LUC7-like 3 pre-mRNA splicing factor (LUC7L3), leading to the production of dysfunctional SCN5a variants associated with heart failure." (PMID 39334823, 2024). "RBM25 also generates an abnormal and truncated splice form of the cardiac voltage-gated Na channel encoded by SCN5A during heart failure." (PMID 33408735, 2020). "In addition, the expression of RBM25 was increased in heart samples from patients with heart failure, and it co-mediated the AS of SCN5A with LUC7L3, thus participating in heart failure and arrhythmia." (PMID 41214391, 2025).
prostate carcinoma (4 papers, 2019 to 2022). A carcinoma that arises from epithelial cells of the prostate gland.
Alzheimer disease (1 paper, 2023). A progressive, neurodegenerative disease characterized by loss of function and death of nerve cells in several areas of the brain leading to loss of cognitive function such as memory and language. "RBM25 is U1 small nuclear ribonucleoprotein with BAD domains and has been suggested to have increased aggregation in Alzheimer’s disease." (PMID 37016304, 2023).
blood disease (1 paper, 2018). A disease that occurs in the blood. "The possibility that RBM11 modulates the splicing of CCND1, and an array of oncogenic genes in EWS, is consistent with known roles for related RNA binding proteins (RBM), including RBM10, RBM15 and RBM25, which alter gene splicing to promote various forms of blood disease and cancer." (PMID 30093970, 2018).
breast carcinoma (1 paper, 2019). "In further support of its tumor suppressor function, RBM25 was previously found to be mutated in breast cancer and to favor the expression of the pro-apoptotic isoform of the BCL2L1 pre-mRNA, the latter via its role in 5ʹ splice site selection in the context of the U1 snRNP20,43,44." (PMID 30635567, 2019).
cardiomyopathies (1 paper, 2015). "Consequently, other RNA-binding proteins such as CELF-3, CELF-5, RBM24, RBM25 and LUC7L3 have been linked to the development of cardiomyopathies." (PMID 26116573, 2015).
colon cancer (1 paper, 2019). "RBM25 expression was significantly greater in colon cancer tissues than in adjacent tissues (P=2.4×10-8)." (PMID 31586988, 2019). "We then analyzed the clinical significance of RBM25 in colon cancer." (PMID 31586988, 2019).
hepatocellular carcinoma (1 paper, 2021). A malignant tumor that arises from hepatocytes. "The regulatory role of RBM25 in hepatocellular carcinoma (HCC) is unknown." (PMID 33830865, 2021).
histiocytic lymphoma (1 paper, 2019). "To do so, we first transduced the U937 cell line (cells with myeloid characteristics and unknown mutational status derived from a patient with histiocytic lymphoma) with lentiviral shRNA vectors targeting RBM25 and tested the effects on proliferation." (PMID 30635567, 2019).
infarction (1 paper, 2025). A localised pathological necrosis of tissue resulting from obstruction of the blood supply usually by a thrombus, an embolus, or vascular torsion. "This study is among the first to identify RBM25 as a regulator of ischemic HF through its modulation of MAP4K4 alternative splicing and downstream activation of the p38 MAPK signaling pathway using a post‐infarction rat model." (PMID 41409803, 2025).
leukemia (1 paper, 2019). A malignant (clonal) hematologic disorder, involving hematopoietic stem cells and characterized by the presence of primitive or atypical myeloid or lymphoid cells in the bone marrow and the blood. "In leukemia, downregulation of RBM25 allows premalignant or malignant cells to harvest the pro-proliferative benefits of MYC (via expression of the BIN(+12) isoform), while at the same time escaping apoptosis (via a shift towards the anti-apoptotic BCL-XL)." (PMID 30635567, 2019).
myocardial infarction (1 paper, 2025). Gross necrosis of the myocardium, as a result of interruption of the blood supply to the area, as in coronary thrombosis. "The findings revealed that the p38 MAPK inhibitor SB203580 markedly reduced the myocardial infarction area caused by RBM25 overexpression." (PMID 41409803, 2025). "Concurrently, this intervention was associated with a significant increase in myocardial infarct size and cardiomyocyte apoptosis rates, effectively abrogating the protective effects conferred by RBM25 silencing alone." (PMID 41409803, 2025). "Compared to the HF‐OE‐NC group, overexpression of RBM25 (HF + OE‐RBM25 group) resulted in a marked increase in myocardial infarction area (p < 0.01)." (PMID 41409803, 2025). "Conversely, inhibition of RBM25 (HF + sh‐RBM25 group) led to a significant reduction in myocardial infarction area compared to the HF + sh‐NC group (p < 0.01)." (PMID 41409803, 2025). "RBM25 overexpression significantly increased myocardial infarction area compared to the HF control group (p < 0.01), while RBM25 knockdown reduced infarct size (p < 0.01)." (PMID 41409803, 2025). "In this study, a HF model was established in SD rats via LAD coronary artery ligation to explore the role of RBM25 in myocardial infarction and HF." (PMID 41409803, 2025). "To further investigate whether RBM25 exacerbates myocardial infarction and thereby promotes the progression of HF through this mechanism, we performed TTC staining on cardiac tissues from eight groups of rats." (PMID 41409803, 2025).
osteosarcoma (1 paper, 2021). A usually aggressive malignant bone-forming mesenchymal neoplasm, predominantly affecting adolescents and young adults. "On the other hand, miR-199a-3p is downregulated in osteosarcoma, and RBM25 may be its potential target gene." (PMID 34820159, 2021).
thyroid cancer (1 paper, 2021). "Therefore, exploring the molecular mechanism of RBM25 in splicing regulation may lead to the development of new treatments for thyroid cancer." (PMID 34249669, 2021).
Virus infection (1 paper, 2026). "Viral infection downregulates RBM25 expression, and RBM25-deficient mice exhibit enhanced susceptibility to multiple viruses and more aggravated tissue damage." (PMID 42299815, 2026). "Virus infection-elicited downregulation of RBM25 results in Rab22a upregulation, which consequently potentiates viral entry." (PMID 42299815, 2026).
tumor (8 papers, 2019 to 2022). "Notably, we found that low RBM25 levels were associated with significantly worse overall survival (OS), consistent with a tumor-suppressive function in human AML." (PMID 30635567, 2019). "RBM25 acts as a tumor suppressor and regulator of MYC activity by controlling the splicing of the MYC inhibitor BIN1." (PMID 36147313, 2022). "The high expression of RBM25 in tumor tissues was significantly related to poor overall survival (P<0.001)." (PMID 33830865, 2021). "RNA-binding motif protein 25 (RBM25) is a poorly characterized RNA-binding protein that is involved in several biological processes and regulates the proliferation and metastasis of tumor cells." (PMID 33830865, 2021). "RBM25 is also reported as a new type of tumor suppressor that can control the splicing of key genes." (PMID 34676158, 2021). "Emerging evidence has demonstrated that RBM25 is essential for several biological processes involved in regulating the proliferation and metastasis of tumor cells." (PMID 33830865, 2021). "The results indicated that high expression of RBM25 in tumor tissues is considerably related to poor OS (P-value = 0.02) in patients with HCC." (PMID 33830865, 2021). "In the present study, we found that the expression of RBM25 is significantly different between normal and tumor samples and significantly affects the survival of patients with HCC." (PMID 33830865, 2021). "A low RBM25 expression level is associated with high MYC activity and poor outcome in AML patients, indicating a tumor suppressor role of RBM25 in AML." (PMID 32806592, 2020). "Our results so far have uncovered a tumor-suppressive function of RBM25 in murine AML and in human cell lines." (PMID 30635567, 2019). "This led to the identification of RBM25, a relatively uncharacterized RNA binding protein, as a potential tumor suppressor." (PMID 30635567, 2019). "Here, the authors perform an in vivo shRNA screen in a CEBPA mutant AML mouse model and identify that RBM25 controls the splicing of pre-mRNAs encoding BCL-X and BIN1 to exert its tumour suppressor activities in AML." (PMID 30635567, 2019). "Among several validated candidates, we focused on RBM25 which we demonstrated to have tumor-suppressive properties in two murine AML models, two human myeloid cell lines and in the hierarchical organized 8227 AML cell culture system." (PMID 30635567, 2019). "Both observations fit well with our demonstration that RBM25 KD results in accelerated tumor progression and delayed myeloid differentiation." (PMID 30635567, 2019). "Overall, these data demonstrate that the tumor-suppressive function of RBM25 that we originally observed in murine AML models can be extended to at least two distinct human models and identifies RBM25 as cross-species regulator of proliferation and apoptosis." (PMID 30635567, 2019). "There was a significant difference in RBM25 gene expression between tumor and normal samples." (PMID 33830865, 2021). "This has led to the identification of the splicing regulator RBM25 as a novel tumor suppressor." (PMID 30635567, 2019). "Having shown that RBM25 acts as a tumor suppressor in murine AML, we now wanted to test if we could expand this to a human setting." (PMID 30635567, 2019). "Furthermore, RBM25 appears to restrict the self-renewal and/or promote the differentiation of immature leukemic cells which is consistent with the tumor suppressive function of the protein." (PMID 30635567, 2019). "Other dysregulated mtFE protein scores in DEN-induced tumor tissue also illustrate apoptotic dysregulation as indicated by increased accumulation of an apoptotic regulator with known nuclear localization in the liver mitochondrial fraction, RNA binding motif protein 25 (Rbm25)." (PMID 31061415, 2019).
tumor (continued). "A total of 139 EC tumor tissues were used to show the positive correlation between the expression of RBM25 and PSI value of SEC23A-27345-AP and ZNF638-53926-AP and the negative correlation between RBM25 and PSI value of SEC23A-27346-AP and ZNF638-53927-AP." (PMID 34676158, 2021).
cancer (5 papers, 2018 to 2023). A tumor composed of atypical neoplastic, often pleomorphic cells that invade other tissues. "A recent study using CRISPR/CAS9-mediated knockout demonstrates that complete loss of RBM25 is detrimental to growth of human cancer cell lines and leads to widespread deregulation of pre-mRNA splicing." (PMID 30635567, 2019). "We found that 30 of these genes which included Nckap1l, Ncf1, Pla2g15, Unc93b1, Lrrc33, Rgs10, Gmfg, Rbm25, C3ar1, Ccdc88b, Fam105a, Gng11, Phc1, Rasa4, Dag1, Tyrobp, Tmsb4x, Cfp, Prkd1, Gp49a, Trem2, C1qc, Lyz2, Igfbp7, Rab30, Cxcl16, Egfl7, Ube2r2, Pltp, and Cfb, showed a relation with cancer." (PMID 32812032, 2020). "Thus, favouring the interaction between RBM25 and the GQ-2 rG4 of BCL-x pre-mRNA represents a relevant intervention point to re-sensitize cancer cells to chemotherapy." (PMID 37811881, 2023).
cardiovascular disease (1 paper, 2025). "Building on the established importance of RBPs in alternative splicing and cardiovascular disease, as well as our prior research in this field, this study further elucidates the regulatory role of RBM25 in HF." (PMID 41409803, 2025).
RBM25 also shares sentences with these, for which no sentence is quoted: Arrhythmia (1 paper); colorectal cancer (1); epilepsy (1); infection (1); ischemic cardiomyopathy (1); lung carcinoma (1).